LAMA5 (laminin subunit alpha 5)
Description:
Binding to cells via a high affinity receptor, laminin is thought to mediate the attachment, migration and organization of cells into tissues during embryonic development by interacting with other extracellular matrix components. Plays a role in the regulation of skeletogenesis, through a mechanism that involves integrin-mediated signaling and PTK2B/PYK2.
Synonyms: BBDS2; NPHS26
Tractability: Antibody: its Gene Ontology location is reachable by antibodies, with high confidence; UniProt places it where antibodies can reach, with medium confidence; UniProt predicts a signal peptide or a membrane-spanning region. PROTAC: ubiquitination databases record sites on it; its protein half-life has been measured. Other modalities: an approved drug acts on it.
Gene: Protein-coding gene on chromosome 20 (62,307,955 to 62,367,312, reverse strand). Ensembl gene ENSG00000130702.
Subcellular location: Secreted, extracellular space, extracellular matrix, basement membrane
Subcellular location (Human Protein Atlas): Vesicles; Predicted to be secreted
Pathways (Reactome):
Extracellular matrix organization: Degradation of the extracellular matrix; ECM proteoglycans; Formation of the dystrophin-glycoprotein complex (DGC); Laminin interactions; Non-integrin membrane-ECM interactions
Developmental Biology: Developmental Lineage of Pancreatic Ductal Cells
Disease: Attachment of bacteria to epithelial cells
Immune System: Interleukin-4 and Interleukin-13 signaling
Signal Transduction: MET activates PTK2 signaling
Gene Ontology:
Molecular function: integrin binding; receptor ligand activity; extracellular matrix structural constituent; signaling receptor binding
Biological process: cell adhesion; cell migration; integrin-mediated signaling pathway; skeletal system morphogenesis; substrate adhesion-dependent cell spreading; regulation of cell adhesion; regulation of cell migration; regulation of embryonic development; animal organ morphogenesis; postsynapse organization; system development
Cellular component: basement membrane; extracellular exosome; extracellular matrix; extracellular region; laminin-10 complex; nucleus; laminin-11 complex; laminin-15 complex; laminin-522 complex; extracellular matrix of synaptic cleft; glutamatergic synapse; neuromuscular junction; synaptic cleft
Genetic constraint (gnomAD): Loss-of-function variants: 254 observed, 361.87 expected, observed/expected ratio (o/e) 0.7, 90% interval 0.63 to 0.78. The synonymous counts are far from expectation, so gnomAD's model fits this gene poorly and the ratio says little. Missense variants: 5,354 observed, 4,844.1 expected, observed/expected ratio (o/e) 1.11, 90% interval 1.08 to 1.13. Synonymous variants: 2,618 observed, 2,054.9 expected, observed/expected ratio (o/e) 1.27, 90% interval 1.23 to 1.32.
Gene-disease validity (ClinGen):
ClinGen rates the evidence that LAMA5 causes each of these diseases.
LAMA5-related multisystemic syndrome (autosomal recessive): Definitive.
Homologues: Orthologues: pig LAMA5 (82% identical), mouse Lama5 (79% identical), rat Lama5 (79% identical), guinea pig LAMA5 (76% identical), chimpanzee LAMA5 (56% identical), zebrafish lama5 (49% identical), tropical clawed frog lama5 (28% identical). Paralogues in human: LAMA3 (38% identical), LAMA2 (21% identical), LAMA1 (20% identical), HSPG2 (16% identical), LAMA4 (14% identical), USH2A (14% identical), LAMC3 (12% identical), LAMC1 (12% identical), LAMB2 (11% identical), LAMB1 (11% identical), LAMB4 (11% identical), AGRN (10% identical), and 15 more.
Diseases named in the same sentence as LAMA5 in open-access papers:
LAMA5 is named in the same sentence as 102 diseases in open-access papers, as found by Europe PMC text mining. Sharing a sentence is not in itself a finding about the gene and the disease. The quoted sentences say what the papers report.
colorectal cancer (19 papers, 2013 to 2025). A primary or metastatic malignant neoplasm that affects the colon or rectum. "LAMA5 encodes for an extracellular matrix glycoprotein and has been suggested as a promoter of liver metastases during colorectal cancer." (PMID 40998421, 2025). "LAMA5 is a molecular target of KRAS-mutated colorectal cancer cells and is overexpressed in the tumor microenvironment (TME)." (PMID 38963646, 2025). "In colorectal cancer, LAMA5 overexpression is associated with hepatic metastasis, angiogenesis, and NOTCH1 pathway inhibition." (PMID 36232418, 2022). "The expression of Laminin 511 was associated with reduced survival in several independent colorectal cancer cohorts and angiogenesis signatures or vessel density significantly correlated with LAMA5 expression." (PMID 31064120, 2019). "The significant colorectal cancer SNP (rs4925386 in LAMA5 gene) has higher derived allele frequency in Africans, but relatively low frequencies in Asians and Europeans." (PMID 27896059, 2013). "Additional studies found that LAMA5 played a role in the interaction of colorectal tumor cells with endothelium and that LAMA5 knockdown in colorectal cancer cells affected differentiation and sensitivity to drug treatment." (PMID 35241737, 2022). "Comparable outcome was obtained for colorectal cancer cell lines, where the presence of LN-332 in the culture medium resulted in reduced expression of the LAMA5 gene." (PMID 34859000, 2021). "Colorectal cancer cells in culture made little LAMA5, but its levels were increased by culture in a medium conditioned by tumour-derived CD11b+ myeloid cells through TNFα/NFκB pathway signalling." (PMID 31064120, 2019). "Elevation of LAMA4/LAMA5 protein ratio correlates with an increase in the permeability of the basal membrane as well as the metastatic and invasive potential of colorectal cancer." (PMID 31781574, 2019). "Overexpression of LAMA5 can induce colorectal cancer through KRAS, while the genetic inactivation of LAMA5 impairs the adhesion of KRAS-mutant colorectal cancer cells." (PMID 29883365, 2018). "Depletion of Lama5 (rs148927246, rs2274933) in lymph node stromal cells controls immunological responses to T cell migration and function, encourages branching angiogenesis, and modifies Notch signaling, which facilitates colorectal cancer spread to the liver." (PMID 38455474, 2024). "Tumor inflammation induces LAMA5 expression in colorectal cancer cells." (PMID 35360846, 2022). "In colorectal cancer, LAMA5 promoted branching angiogenesis and liver metastasis." (PMID 35241737, 2022). "The NF-κB pathway has been reported to be a positive regulator of LAMA5 in colorectal cancer cells." (PMID 35267534, 2022). "Interestingly, seven of the shared significant genes have been associated to colorectal cancers, including UTP23, GREM1, SCG5, SMAD7, CABLES2, LAMA5, and PREX1." (PMID 32245788, 2020). "BCAM is highly expressed in KRAS-mutant hepatic metastases from colorectal cancer, and inhibition of BCAM/LAMA5 interferes with the adhesion of colorectal cells to vascular endothelial cells, thereby reducing metastatic growth." (PMID 36672394, 2023). "Genes such as LAMA4, LAMA5, and C1QTNF6 were involved in angiogenesis in many cancer types such as renal cell carcinoma, colorectal cancer, and hepatocellular carcinoma, but these genes may be linked with angiogenesis in GBM." (PMID 31137733, 2019).
nephrotic syndrome (10 papers, 2016 to 2025). A collection of symptoms that include severe edema, proteinuria, and hypoalbuminemia; it is indicative of renal dysfunction. "Biallelic LAMA5 variants have been identified in one adult and ten pediatric nephrotic syndromes (NS) patients with variable phenotypes." (PMID 36714636, 2023). "Podocytes specific inactivation of Lama5 in mice, results in varying degrees of proteinuria and progression to nephrotic syndrome likely related to a thickening of the GBM associated with podocyte foot processes disruption." (PMID 30808327, 2019). "We identified a missense mutation (E884G) in the Lama5 gene that results in a progressive nephrotic syndrome." (PMID 27534441, 2016). "Here, we have identified a novel missense mutation (E884G) in the uncharacterized L4a domain of LAMA5 where homozygous mice develop nephrotic syndrome with severe proteinuria with histological and ultrastructural changes in the glomerulus mimicking the progression seen in most patients." (PMID 34774562, 2022). "Mutations in LAMA5 were recently identified in children with nephrotic syndrome." (PMID 34774562, 2022). "Variants in LAMA5 were recently identified in children with nephrotic syndrome." (PMID 33745160, 2021). "Thus, this novel mutant provides supporting evidence for a role for LAMA5 in nephrotic syndromes and will enable the investigation of the pathogenic processes involved." (PMID 27534441, 2016). "Four patients (LAMB2, LAMA5 and PLCE1 variants) presented with nephrotic syndrome or nephrotic range proteinuria." (PMID 40003707, 2025). "LAMA3-related diseases include laryngeal cartilage skin syndrome and epidermolysis bullosa, LAMA4-related diseases include cardiomyopathy, while LAMA5-related diseases include peripheral retinal degeneration and nephrotic syndrome." (PMID 32213190, 2020). "Podocyte-specific inactivation of Lama5 in mice, resulted in varying degrees of proteinuria and rates of progression to nephrotic syndrome." (PMID 29764427, 2018). "For instance, it has been reported in the last two years that LAMA5 variants are co-inherited with COL4A5 variants in familial hematuria, and such co-inheritance might affect pediatric nephrotic syndrome." (PMID 32386536, 2020).
breast carcinoma (6 papers, 2013 to 2025). "LAMA5 is vital in the migration of many cancers, including breast carcinoma, fibrosarcoma, and colon cancer." (PMID 38963646, 2025). "Additional recurrently mutated genes detected in the 16 PALB2-associated breast cancers profiled by WES included CTNNA2, TMPRSS13, KRTAP4–11, LAMA5, KALRN, and COLL22A1 (all, n = 3)." (PMID 31428676, 2019).
colon carcinoma (5 papers, 2019 to 2025). "Our PheWAS results also indicate the index variants at LAMC1 and LAMA5 are significantly associated with colon cancer." (PMID 38582945, 2024). "The reduction in LAMA5 was associated with a significant reduction in liver metastatic burden following intrasplenic injection of colon cancer cells." (PMID 31064120, 2019). "Consequently, the profound effect on vascular morphology and function upon LAMA5 mutation and inhibition of LAMA5 expression specifically by colon cancer cells indicates that cancer cell Laminin 511 deposition is important for colonic cells, promoting angiogenesis." (PMID 37627102, 2023). "In this context, it is noteworthy that KRAS‐mutated colon carcinoma cells express high levels of BCAM and efficiently form hepatic metastases in mice, which is inhibited by BCAM‐mimetic peptides blocking LAMA5–BCAM interaction." (PMID 36647260, 2023). "In primary colon cancer and liver metastasis resection specimens, LAMA5 and LAMB1 were strongly expressed within the vascular basement membrane where they encased the tumour vasculature similar to the pattern in the orthotopic tumours." (PMID 31064120, 2019). "We introduced shRNA-targeting LAMA5 (denoted LAMA5sh) to colon cancer cells which resulted in a significant reduction in LAMA5 protein expression in transfected cells." (PMID 31064120, 2019). "Conditioned media from myeloid cells extracted from the liver metastatic microenvironment contained an array of inflammatory cytokines and promoted the expression of LAMA5 in colon cancer cells." (PMID 31064120, 2019). "To investigate these findings further, we assessed the effect of CD11b+ myeloid cell-conditioned media on LAMA5 expression by colon cancer cells." (PMID 31064120, 2019). "We next explored the potential mechanisms that regulate LAMA5 expression in colon cancer cells." (PMID 31064120, 2019). "Laminin α5 (LAMA5) expression was inhibited in colon cancer cells using shRNA." (PMID 31064120, 2019). "Immunohistochemical staining of orthotopic hepatic metastases and subcutaneous colon cancers in mice using an antibody specific for human LAMA5 demonstrated expression in a discontinuous pattern on the basolateral surface of cancer cells in close association with murine collagen type IV." (PMID 31064120, 2019). "To investigate the potential stimuli that drive LAMA5 expression in colon cancer cells, we chose to analyse the role of infiltrating immune cells as we previously found them to be potent activators of angiogenesis in liver metastases and immune cells are key regulators of tumour ECM deposition." (PMID 31064120, 2019). "Whilst we could phenocopy the effect of myeloid cell-conditioned media with recombinant TNFα alone, with respect to LAMA5 in colon cancer cells, it remains to be determined whether other factors produced by tumour-derived myeloid cells can similarly drive LAMA5 expression." (PMID 31064120, 2019). "In support of the increased cancer-specific production of these laminin chains, we identified significantly greater expression of LAMA5, LAMB1 and LAMC1 transcripts in colon cancer tissues compared with normal colon in publicly available gene array data using the OncomineTM platform." (PMID 31064120, 2019). "The treatment of colon cancer cells with TNF-α resulted in an increase in LAMA5 expression; an effect not demonstrated in endothelia." (PMID 31064120, 2019). "Among others, human LAMA5, LAMB1 and LAMC1 transcripts were expressed at high levels, with little or no expression of human collagen IV identified, indicating that the laminins required for vascular basement membrane assembly are produced by metastatic colon cancer cells." (PMID 31064120, 2019).
ovarian carcinoma (5 papers, 2019 to 2024). A malignant neoplasm originating from the surface ovarian epithelium. "In ovarian cancer, LAMA5 overexpression was associated with a good prognosis." (PMID 36232418, 2022). "ETS1 overexpression altered the size of exosomes derived from ovarian cancer cells, and upregulated the expression of three laminins, LAMA5, LAMB1, and LAMC1, in ovarian cancer cells and their exosomes." (PMID 36477408, 2022). "In ovarian cancer samples from the TCGA database, the expression levels of LAMA5, LAMB1, and LAMC1 were positively correlated with that of ETS1." (PMID 36477408, 2022). "The laminin family members LAMA5, LAMB1, and LAMC1 were the most prominently upregulated proteins in LV-ETS1 Exos of the two ovarian cancer cell lines." (PMID 36477408, 2022). "In a survival analysis of patients with ovarian cancer in the GSE9891 dataset, increased expression of LAMA5, LAMB1, and LAMC1 was related to shorter overall survival." (PMID 36477408, 2022). "The results show that ETS1 transcriptionally regulates the expression of LAMA5, LAMB1, and LAMC1 in ovarian cancer cells." (PMID 36477408, 2022). "According to qRT-PCR and western blotting data, ETS1 regulated the expression of LAMA5, LAMB1, and LAMC1 in ovarian cancer cells." (PMID 36477408, 2022).
myopia (4 papers, 2018 to 2025). "There are two reports that describe severe neuromuscular transmission failure and/or myopia, facial tics, and failure of neuromuscular transmission in patients with LAMA5 mutation as homozygous status." (PMID 30631761, 2018). "In a female with a LAMA5-variant, myopia and facial tics were described." (PMID 30808424, 2019). "Lama5-p.R1565C (homologous to p.R1560C in humans) mice exhibited myopia from P28 to P70 compared with WT mice (all P < 0.001)." (PMID 40040800, 2025).
congenital myasthenic syndrome (3 papers, 2018 to 2022). Congenital myasthenic syndrome (CMS) is a group of genetic disorders of impaired neuromuscular transmission at the motor endplate characterized by fatigable muscle weakness. "One pair of homozygous variants in LAMA5 (p.Arg2659Trp) and one homozygous variant in LAMA1 were identified in a patient with the presynaptic congenital myasthenic syndrome who has non-classified facial tics or tics." (PMID 35663266, 2022).
focal segmental glomerulosclerosis (3 papers, 2018 to 2025). A renal disorder characterized by sclerotic lesions in the glomeruli. "Mutations in COL4A5 cause classical X-linked Alport Syndrome, while rare mutations in the LAMA5 have been reported in patients with focal segmental glomerulosclerosis." (PMID 29764427, 2018). "Two patients (LAMB2 and LAMA5 variants) were diagnosed with focal segmental glomerulosclerosis." (PMID 40003707, 2025). "We performed whole-exome sequencing analyses of a family with slowly progressive nephropathy associated with hereditary focal segmental glomerulosclerosis, and we identified what we believe to be a novel probable pathogenic variant of LAMA5, NP_005551.3:p.Val3687Met." (PMID 36173685, 2022).
gastric cancer (3 papers, 2021 to 2022). A primary or metastatic malignant neoplasm involving the stomach. "Interestingly, also LAMA5 that promotes colorectal liver metastasis growth, resulted upregulated in intestinal gastric cancer." (PMID 34012923, 2021). "No information about the potential use of LAMA5 as a biomarker for prognosis in gastric cancer has been reported." (PMID 36232418, 2022).
Alport syndrome (2 papers, 2018 to 2022). A rare renal disease characterized by glomerular nephropathy with hematuria progressing to end-stage renal disease (ESRD), frequently associated with sensorineural deafness, and occasionally with ocular anomalies. "For instance, in Alport’s syndrome, mutations in Lama4, Lama5, or collagen IV genes disrupt or enlarge basement membrane pores leading to severe leakage of plasma proteins into the urine, known as proteinuria." (PMID 36073544, 2022). "A modifier role of LAMA5 on the background of a hypomorphic Alport syndrome causing mutation is a possible explanation of our findings." (PMID 29764427, 2018). "Probably, the easiest way is screening for mutations or for modifier variants in the LAMA5 gene in multiple FMH and Alport syndrome families." (PMID 29764427, 2018).
clear cell renal cell cancer (2 papers, 2021 to 2023). "For instance, IGF2BP3 enhanced the proliferative activity of clear cell renal cell cancer cells by increasing the expression of cyclin-dependent kinase 4, collagen type VI alpha 1 chain, laminin subunit alpha 5, and fibronectin 1 in an m6A-dependent manner." (PMID 34621671, 2021). "In clear cell renal cell carcinoma, the complex of IGF2BP3/lncRNA DMDRMR selectively interacts with their m6A-modified co-targets (including CDK4, COL6A1, LAMA5, and FN1) to promote cell proliferation." (PMID 37280679, 2023).
colorectal tumor (2 papers, 2018 to 2022). "High LAMA4/LAMA5 ratio is associated with increased permeability of basement membranes suggesting that basement membranes produced by colorectal tumors might be an important hindrance to their own dissemination in patients." (PMID 29504916, 2018).
COVID-19 (2 papers, 2023 to 2026). A disease caused by infection with severe acute respiratory syndrome coronavirus 2. "The most changed components of BM included laminins (LAMB2, LAMA2, LAMC3, LAMB1, LAMC1, and LAMA5) and proteoglycans (COL18A1, HSPG2, and AGRN), with some BM specific collagens (IV, VIII, XVIII, and V collagens) remaining in COVID-19 brains, as compared with the control brains." (PMID 36609561, 2023).
epidermolysis bullosa (2 papers, 2014 to 2020). Epidermolysis bullosa (EB) is a group of genetic skin diseases that cause the skin to blister very easily. "This possibility is supported by a LAMA5 gene mutation in the epidermolysis bullosa characterized by skin fragility and enamel dysplasia, as a result of the destruction of dermal and dental epithelia, respectively." (PMID 25601840, 2014).
familial hematuria (2 papers, 2018 to 2020). "This is the third report linking a LAMA5 variant with human renal disease and expanding the spectrum of genes involved in glomerular pathologies accompanied by familial hematurias." (PMID 29764427, 2018).
glomerulopathy (2 papers, 2022 to 2025). "A homozygous pathological variant in LAMA5 is known to cause a systemic developmental syndrome including glomerulopathy." (PMID 36173685, 2022).